NEAT1 (nuclear paraspeckle assembly transcript 1)
Diseases named in the same sentence as NEAT1 in open-access papers (continued):
Sharing a sentence is not in itself a finding about the gene and the disease.
lung cancer (continued). "As we have demonstrated, TLR4/NF-κB/NEAT1 can be activated by LPS stimulation; are there any other dysregulated factors in lung cancer that can modulate this TLR4/NF-κB/NEAT1 axis?" (PMID 29788922, 2018). "Clinically, Oct4/NEAT1/MALAT1 co-overexpression was an independent factor for prediction of poor outcome in 124 lung cancer patients." (PMID 28615056, 2017). "Clinical studies further validated the importance of Oct4/NEAT1/MALAT1 signaling axis in lung cancer progression." (PMID 28615056, 2017). "After adjusting for late stage and lymph node metastasis using multivariate Cox regression analysis, co-overexpression of Oct4, NEAT1 and MALAT1 in lung cancer patients showed a relative risk of death of 2.42 (P = 0.039)." (PMID 28615056, 2017). "These clinical studies clearly indicated that Oct4 positively correlates with NEAT1 and MALAT1 expression in lung cancer and that Oct4/NEAT1/MALAT1 co-overexpression is an independent factor for prediction of poor outcome in lung cancer patients." (PMID 28615056, 2017). "Meanwhile, alterations of PVT1 and NEAT1 will reduce the overall survival and disease free survival in lung cancer." (PMID 28938549, 2017). "A role for NEAT-1 has been described in several types of cancers such as breast, prostate, and lung cancer, with effects on promoting tumor growth through genetic or epigenetic mechanisms." (PMID 28122578, 2017). "Of note, positive correlations between Oct4 mRNA and NEAT1/MALAT1 lncRNAs were evident in lung cancer patient specimens." (PMID 28615056, 2017). "In terms of chemo-resistance, NEAT1 was found to up-regulated EGCG-induced CTR1 to enhance cisplatin sensitivity in lung cancer cells." (PMID 27926523, 2017). "We showed that lung cancer cells overexpressing NEAT1 or MALAT1 and the Oct4-silenced cells reconstituted with NEAT1 or MALAT1 promoted cell proliferation, migration and invasion." (PMID 28615056, 2017). "A novel mechanism of decreasing drug resistance in lung cancer by EGCG, was proved to be via NEAT1 upregulation, leading to an increased response to cisplatin and preventing activation of drug resistance mechanisms in lung cancer." (PMID 28587155, 2017). "Using the same method, the expression of lncRNAs MALAT1, BANCR, NEAT1 in primary lung cancer were also analyzed." (PMID 28938549, 2017). "In the differentially expressed lncRNAs, BANCR, kucg 1, MALAT1, NEAT1 were chosen for further study in lung cancer." (PMID 28938549, 2017). "NEAT1 upregulation has been reported in human malignancies, including leukemia, hepatocellular carcinoma and lung cancers." (PMID 26822763, 2016). "Consistent with our results, NEAT1 was reported to be upregulated in non-small cell lung cancers and to promote lung cancer cell growth." (PMID 27556696, 2016). "LncRNA NEAT1 dysregulation has been reported in various cancers such as malignant glioma, esophageal carcinoma, colorectal carcinoma and lung cancer." (PMID 27270317, 2016). "Similarly, another study reported that lncRNA NEAT1 interacts with DNMT1 to regulate cytotoxic T cell infiltration by inhibiting cGAS/STING pathway in lung cancer." (PMID 40308809, 2025). "Concordantly, our recently published Non-Small Cell Lung Cancer (NSCLC) scRNA-seq atlas revealed that MALAT1 and NEAT1 are highly abundant in various cells of the lung cancer TME and noticeable higher expressed in datasets generated with 10X Chromium compared to BD Rhapsody, respectively." (PMID 38689972, 2024). "The upregulation of NEAT1 in lung cancer tissues has been observed in several studies." (PMID 36011001, 2022). "An upregulation of NEAT1 could be observed in the majority of solid tumors such as lung cancer, esophageal cancer and hepatocellular carcinoma, and NEAT1 also plays a critical role in neurodegenerative diseases and viral infection." (PMID 35625576, 2022).
lung cancer (continued). "Moreover, in lung cancer, NEAT1 competed against let-7a to contribute to nonsmall-cell lung cancer proliferation and metastasis, and another research in lung cancer also revealed downregulation of NEAT1 led to cell invasion in NSCLC via sponging miR-153-3p." (PMID 36262350, 2022). "In lung cancer cell lines, down-regulation of NEAT1 could decrease the expression of stemness-related factors, including CD133, CD44, SOX2, OCT4 and NANOG." (PMID 33614649, 2021). "LncRNA NEAT1 was also reported to be upregulated in lung cancer tissues with high TILs." (PMID 35047506, 2021). "MALAT1 and NEAT1 have been widely studied non-coding RNAs, and some studies have demonstrated that they have clear correlations with various cancers such as hepatocellular carcinoma and lung cancer." (PMID 33499813, 2021). "miRNA-449a is able to inhibit cell growth in lung cancer and mediate NEAT1." (PMID 33393590, 2021). "Given that silencing of NEAT1 could inhibit the cell viability of lung cancer cells in vitro, its function in vivo was also determined." (PMID 32296457, 2020). "However, we should admit that there are still obstacles for NEAT1 to be applied in diagnose or treatment of lung cancer due to the limitation of detection of non-coding RNAs." (PMID 32296457, 2020). "Given that NEAT1 was involved in lung cancer tumorigenesis and metastasis, we next investigated whether ATF2 exerted its oncogenic role through upregulating NEAT1." (PMID 33298086, 2020). "Collectively, NEAT1 was upregulated in lung cancer tissues and cell lines." (PMID 32296457, 2020). "Having demonstrated that NEAT1 promoted growth and migration/invasion of lung cancer cells, we speculated whether blocking of DNMT1 was able to reverse the protumor effect of lncRNA NEAT1." (PMID 32296457, 2020). "The NEAT1 inhibition suppresses the lung cancer cell survival, migration, and invasion." (PMID 33643304, 2020). "It was shown that NEAT1 was highly expressed in lung cancer tissue and cells." (PMID 32296457, 2020). "The aberrant expression was closely associated with tumor stage and lymph node metastasis, suggesting that NEAT1 could be involved in the progression of lung cancer." (PMID 32296457, 2020). "The results showed that NEAT1 was overexpressed in lung cancer tissues and cancer cell lines." (PMID 32296457, 2020). "Under most circumstances, NEAT1 functions as a oncogene in different malignancies, such as lung cancer, oesophageal squamous cell carcinoma, laryngeal squamous cell carcinoma, ovarian cancer, colorectal cancer, hepatocellular carcinoma, prostate cancer, and glioma." (PMID 30894512, 2019). "NEAT1 could also be activated by Oct4’s binding to its promoter, which therefore led to lung cancer progression and poor prognosis outcome." (PMID 30053878, 2018). "Herein, we hypothesized that Galectin-3 may activate TLR4/NF-κB/NEAT1, thereby affecting lung cancer cell proliferation and migration." (PMID 29788922, 2018). "Consistent with previous studies, NEAT1 may contribute to lung cancer cell proliferation and migration; thus, inhibiting aberrant NEAT1 overexpression in lung cancer represents a promising strategy for regulating cancer cell growth." (PMID 29788922, 2018). "Herein, we investigated whether TLR4 is another component of the upstream regulatory signaling of NEAT1 expression in lung cancer cell lines." (PMID 29788922, 2018). "After NEAT1 knockdown, the cell viability and DNA synthesis capacity of A549 and H1299 was significantly suppressed, indicating that NEAT1 knockdown could inhibit lung cancer cell proliferation." (PMID 29788922, 2018). "For example, it has been reported that NEAT1 can promote lung cancer progression through the miR-377-3p–E2F3 axis, regulate EMT through the miR-204/ZEB1 pathway in nasopharyngeal carcinoma, and serves as a downstream target of ERα to play a critical role in carcinogenesis of prostate cancer." (PMID 29515109, 2018).
lung cancer (continued). "In the present study, we reported abnormal lncRNA-NEAT1 overexpression in lung adenocarcinoma specimens; NEAT1 knockdown could inhibit lung cancer cell proliferation and migration." (PMID 29788922, 2018). "Moreover, Oct4-mediated high expression of lncRNAs such as nuclear paraspeckle assembly transcript 1 (NEAT1) and metastasis-associated lung adenocarcinoma transcript 1 (MALAT1) promoted lung cancer cell proliferation, migration and invasion abilities." (PMID 28615056, 2017). "In our study, we have shown that a well-known stemness transcription factor Oct4 transcriptionally upregulates NEAT1 expression through binding to Oct4 consensus binding element on promoter region, and therefore promoting lung cancer proliferation and motility." (PMID 28615056, 2017). "In addition, knockdown of NEAT1 or MALAT1 abolished Oct4-mediated lung cancer cell growth and motility." (PMID 28615056, 2017). "Our study showed that NEAT1 could function as a competing endogenous lncRNA in lung cancer, mediating CTR1 by sponging hsa-mir-98-5p." (PMID 27270317, 2016). "In lung cancer, NEAT1 is regulated by microRNA-449a, which can inhibit tumor cell growth." (PMID 27270317, 2016). "However, the association of NEAT1 with the survival of patients with lung cancer has not been reported previously." (PMID 32819367, 2020). "Similarly, MALAT1, UCA1, ANRIL, and NEAT1 were shown to predict lung cancers." (PMID 31141943, 2019). "Moreover, NEAT1 knockdown also suppressed the migration capability of lung cancer cell." (PMID 29788922, 2018). "However, lung cancer had higher NEAT1 expression, when compared with primary lung cancer." (PMID 28938549, 2017). "However, Oct4 did not affect the activity of NEAT1 promoter with Oct4 binding element mutated in both lung cancer cells (green bars)." (PMID 28615056, 2017). "Moreover, NEAT1 was reported to be regulated by miR-449a in lung cancer." (PMID 26822763, 2016). "So, NEAT1, by interacting with DNMT1, inhibits the cGAS/STING pathway, thereby regulating cytotoxic T cell infiltration in lung cancer." (PMID 40387409, 2025). "Oct4 transcriptionally activates the expression of NEAT1 and MALAT1 to accelerate the progression of lung cancer." (PMID 40115023, 2025). "Immune cell-specific lncRNAs such as NEAT1 play a role in modulating immune responses and inflammation, which are critical in both COPD and lung cancer." (PMID 39201688, 2024). "For example, Oct4 transcriptionally activates the expression of NEAT1 and MALAT1 to accelerate lung cancer progression." (PMID 38430256, 2024). "Another lncRNA, NEAT1, interacts with DNMT1, orchestrating cytotoxic T cell infiltration in lung cancer." (PMID 37880732, 2023). "In the context of lung cancer, it has been recently demonstrated that OCT4, a key stemness transcription factor, promotes NEAT1 and MALAT1 transcription by targeting their promoter and enhancer regions." (PMID 35814429, 2022). "The coexpression of OCT4, NEAT1 and MALAT1 can also be used to predict the prognosis of lung cancer patients." (PMID 35907897, 2022). "In lung cancer cells, overexpression of OCT4 upregulated the transcriptional activity of the NEAT1 promoter and MALAT1 enhancer, as well as their expression." (PMID 35907897, 2022). "In the case of NEAT1, the transcription of this lncRNA is positively modulated by HIF-2α in lung cancer." (PMID 34298879, 2021). "In lung cancer cells, NEAT1 and MALAT1 have been proved to be downstream effectors of Oct4-induced lung cancer proliferation, migration and invasion." (PMID 33298086, 2020). "In 2019, Wu recently found that NEAT1 was involved in the axis of NEAT1/has-miR-98-5p/MAK6, and its over-expression in tumor cells promoted lung cancer development." (PMID 31462890, 2019).
lung cancer (continued). "Silencing of NEAT1 reduced cancer stem cell-like properties in lung cancer stem cells and CTR1 expression was negatively correlated with NEAT1 expression." (PMID 30894512, 2019). "For example, MALAT1, a critical regulator of the metastasis phenotype in lung cancer cells, potentially regulated the expression of UBN2 and NEAT1 (row two)." (PMID 29303984, 2018). "Galectin-3 activates TLR4 signaling thus affecting lung cancer cell proliferation and migration through TLR4/NF-κB/NEAT1." (PMID 29788922, 2018). "In regards to chemo-resistance, NEAT1 was found to upregulate EGCG-induced CTR1 and enhance cisplatin sensitivity in lung cancer cells." (PMID 30154460, 2018). "One of these is nuclear-enriched abundant transcript 1 (NEAT1), which is a highly conserved nuclear lncRNA and a predictive marker for metastasis in lung cancer." (PMID 28177876, 2017). "The results suggested that Oct4/NEAT1 and Oct4/MALAT1 transcriptional axes promote oncogenic effects in lung cancer." (PMID 28615056, 2017). "NEAT1 and MALAT1 function as Oct4 downstream mediators to promote lung cancer proliferation, migration and invasion." (PMID 28615056, 2017). "The overexpression rate for Oct4, NEAT1 and MALAT1 RNA were 85.5%, 90.3% and 88.7%, indicating the oncogenic roles of Oct4, NEAT1 and MALAT1 in lung cancer patients." (PMID 28615056, 2017). "Since oncogenic lncRNAs, NEAT1 and MALAT1, were positively regulated by Oct4 at transcriptional level, we further characterized the oncogenic roles of NEAT1 and MALAT1 lncRNAs in lung cancer cells." (PMID 28615056, 2017). "Recent studies have suggested that many lncRNAs are of great importance in lung cancer, such as HOTAIR, NEAT1 and PVT1." (PMID 28981099, 2017). "On the other hand, the interactions between the Neat1 SNPs rs512715 and rs2239895 and cigarette smoking were not statistically significant in lung cancer patients." (PMID 40027195, 2025). "Similarly, researchers have indicated that lncRNA NEAT1 is upregulated by (-)-epigallocatechin-3-gallate (EGCG)-induced oxidative stress, increasing cisplatin intake in lung cancer treatment." (PMID 37258567, 2023). "Furthermore, NEAT1 and MALAT1 function as downstream mediators of OCT4 to promote proliferation, migration and invasion of lung cancer cells." (PMID 35814429, 2022). "NEAT1 can be a competing endogenous lncR that upregulates EGCG-induced CTR1 by sponging miR-98-5p in these cells, suggesting that EGCG is an effective chemotherapeutic agent in the lung cancer treatment." (PMID 36552560, 2022). "Some LncRNAs including HOTAIR, MALAT1, NEAT1, and NNT‐AS1 have been involved in cisplatin resistance, through WNT and/or MAPK/Slug intracellular signaling pathways, as well as promoting malignancy in solid lung tumors, and lung cancer cell lines." (PMID 33433063, 2021). "In lung cancer, both LINC01436 and NEAT1 facilitate cell migration and invasion." (PMID 34298879, 2021). "In addition, qRT-PCR analysis showed that NEAT1 expression in LUAD tissues and cell lines was increased compared with normal lung cancer tissues and normal bronchial epithelial cell line, respectively." (PMID 33298086, 2020). "Reverse transcription qPCR analysis revealed that the expression of NEAT1 was remarkably increased in 32 lung cancer tissues compared with 32 respective adjacent non-cancerous tissues." (PMID 32296457, 2020). "Given that Galactin-3 positively regulates TLR4 protein expression, as well as the proliferation and migration of lung cancer cell lines; next, we investigated whether Galectin-3 acts through TLR4/NF-κB/NEAT1." (PMID 29788922, 2018).
lung cancer (continued). "Moreover, NEAT1 and MALAT1 function as Oct4 downstream mediators to promote lung cancer proliferation, migration and invasion." (PMID 28615056, 2017). "Moreover, NEAT1 and MALAT1 acted as downstream effectors of Oct4 to promote proliferation, migration and invasion abilities of A549 lung cancer cells." (PMID 28615056, 2017). "To further validate Oct4/NEAT1 and Oct4/MALAT1 transcriptional axes in lung cancer patients, we examined RNA expression level of Oct4, NEAT1 and MALAT1 using qRT-PCR analysis of samples from 124 lung cancer patients." (PMID 28615056, 2017). "Upregulated XIST, MALAT1, and NEAT1 lncRNAs were predicted to modulate and promote cell development and further metastasis in multiple cancers through mir-124-3p, but no studies in lung cancer were done regarding other functions of these lncRNAs, or their response to VRB." (PMID 38137519, 2023). "Moreover, MiR-223 and NEAT1 both have promoting roles for lung cancer carcinogenesis and COPD, and whether they are also involved in COPD complicated with lung cancer remains to be determined." (PMID 38025954, 2023). "NEAT1 is abnormally expressed in lung cancer and acts as an oncogene; herein, we first validated NEAT1 expression in 83 paired lung adenocarcinoma and adjacent normal specimens, as well as its correlation with the overall survival in patients with lung adenocarcinoma." (PMID 29788922, 2018). "Our findings reveal a novel mechanism how NEAT1 upregulates EGCG-induced CTR1 and enhances cisplatin sensitivity in vitro and in vivo, and suggest EGCG could serve as an effective adjuvant chemotherapeutic in lung cancer treatment." (PMID 27270317, 2016). "Interestingly, MALAT1 and Nuclear Paraspeckle Assembly Transcript 1 (NEAT1) are also transcriptionally regulated by OCT3/4, with evidence that OCT3/4 binds to the promoter of MALAT1 while acting as an enhancer for NEAT1, thereby increasing their expression in lung cancer." (PMID 39062685, 2024). "However, the role of NEAT1 in lung cancer has not been explored." (PMID 27270317, 2016). "Particularly, H19, NEAT1, SNHG1, and TUG1 were significantly more expressed in lung cancer patients from both AA and WA lung cancer patients compared to those without cancer." (PMID 38791954, 2024).